CLRN1 (clarin 1)
Description:
May have a role in the excitatory ribbon synapse junctions between hair cells and cochlear ganglion cells and presumably also in analogous synapses within the retina.
Synonyms: USH3A; RP61; USH3
Tractability: Antibody: UniProt places it where antibodies can reach, with high confidence; its Gene Ontology location is reachable by antibodies, with high confidence; UniProt predicts a signal peptide or a membrane-spanning region.
Gene: Protein-coding gene on chromosome 3 (150,926,163 to 150,972,727, reverse strand). Ensembl gene ENSG00000163646.
Subcellular location: Cell membrane
Subcellular location (Human Protein Atlas): Centrosome; Basal body; Vesicles
Gene Ontology:
Molecular function: protein binding
Biological process: actin filament organization; cell motility; equilibrioception; photoreceptor cell maintenance; positive regulation of lamellipodium assembly; sensory perception of light stimulus; sensory perception of sound; neuromuscular process controlling balance
Cellular component: lamellipodium; microvillus; plasma membrane; actin-based cell projection; basal part of cell; microtubule cytoskeleton; stereocilium; trans-Golgi network transport vesicle
Genetic constraint (gnomAD): Loss-of-function variants: 15 observed, 19.77 expected, observed/expected ratio (o/e) 0.76, 90% interval 0.51 to 1.17. The upper end of that interval is the gene's LOEUF score, 1.17, which puts it in group 5 of 6, group 1 being the genes least tolerant of losing a copy. Missense variants: 311 observed, 293.69 expected, observed/expected ratio (o/e) 1.06, 90% interval 0.96 to 1.16. Synonymous variants: 104 observed, 108.22 expected, observed/expected ratio (o/e) 0.96, 90% interval 0.82 to 1.13.
Gene-disease validity (ClinGen):
ClinGen rates the evidence that CLRN1 causes each of these diseases.
Usher syndrome type 3 (autosomal recessive): Definitive. A syndrome characterized by postlingual progressive hearing loss, abnormalities in the vestibular system, and onset of retinitis pigmentosa symptoms usually by the second decade of life.
Homologues: Orthologues: chimpanzee CLRN1 (99% identical), macaque CLRN1 (97% identical), guinea pig CLRN1 (94% identical), pig CLRN1 (94% identical), rabbit CLRN1 (94% identical), dog CLRN1 (92% identical), rat Clrn1 (90% identical), mouse Clrn1 (89% identical), tropical clawed frog clrn1 (68% identical), zebrafish clrn1 (61% identical), Drosophila melanogaster CG1103 (18% identical), Caenorhabditis elegans Y67D8C.22 (17% identical). Paralogues in human: CLRN2 (35% identical), CLRN3 (22% identical).
Diseases named in the same sentence as CLRN1 in open-access papers:
CLRN1 is named in the same sentence as 37 diseases in open-access papers, as found by Europe PMC text mining. Sharing a sentence is not in itself a finding about the gene and the disease. The quoted sentences say what the papers report.
Usher syndrome (41 papers, 2009 to 2025). A syndromic diseae characterized by the association of sensorineural deafness (usually congenital) with retinitis pigmentosa and progressive vision loss. "Usher syndrome is caused by mutations in the CLRN1 gene, which is thought to play a role in the development and maintenance of photoreceptor cells and inner ear hair cells." (PMID 39060957, 2024). "Pathogenic variants in CLRN1 (clarin 1) cause either non-syndromic retinitis pigmentosa (RP) or Usher syndrome type 3A (USH3A), that is characterized by progressive hearing loss, RP and variable vestibular dysfunction." (PMID 33496845, 2021). "The frequency of Usher syndrome due to mutations in CLRN1 in our sample is 18% (two out of 11), considerably higher than the 5% or less in other populations." (PMID 31231422, 2019). "Usher syndrome resulting from mutations in CLRN1 is rare except in Finland and among the Ashkenazi jews, and its high frequency among USH3 patients in these populations is due to founder mutations." (PMID 31231422, 2019). "With only 30 supposedly pathogenic variants annotated in the Human Gene Mutation Database22, the CLRN1-associated subtype of Usher syndrome, USH3A, is very rare." (PMID 28469144, 2017). "While the function of this protein is poorly understood, mutations in a paralog, Clarin 1, have been associated with Usher syndrome, which causes loss of vision and hearing." (PMID 27569060, 2016). "Separately, in-vitro expression of missense mutations of CLRN1, a gene associated with Usher syndrome, is retained within the ER." (PMID 26987071, 2016). "Mutations in CDH23, PCDH15, VLGR1 and clarin-1 cause Usher syndrome, characterized by congenital deafness, vestibular dysfunction and retinitis pigmentosa." (PMID 22363448, 2012). "In LER (CD−M2), Ush1c, Otogl, Gjb2, and Eps8 were associated with NSHL; Ush1c and Clrn1 with Usher syndrome, Six1 with branchiootorenal syndrome; Gjb2 with skin phenotype and HL; Gata3 with hypoparathyroidism, sensorineural hearing loss, and renal dysplasia; and Col9a2 with Stickler syndrome." (PMID 39684410, 2024). "A pathophysiology shared between the vestibular and visual systems presents itself when clarin-1 is incapable of proper intracellular trafficking and plasma membrane insertion, causing deafness and RP in Usher syndrome patients and have been linked to deletions in both exon 2 and 3 of USH3A." (PMID 36830640, 2023). "In addition to USH2A, mutations in CLRN1 are also known to cause both Usher syndrome and NSRP33." (PMID 28894305, 2017). "Targeted exome sequencing identified four distinct genotypes and likely pathogenic sequence variants in cell lines derived from clinically diagnosed Usher syndrome patients: MY07A, CDH23, USH2A, and CLRN1." (PMID 39337481, 2024). "Aside from DFNB9, current efforts target Usher Syndrome Type 3A (defects of CLRN1 coding for clarin‐1), DFNB8 (defects of TMRPSS3 coding for Transmembrane protease serine 3), and DFNB16 (defects of STRC coding for stereocilin)." (PMID 35833443, 2022). "The “rarest” Usher syndrome genes with mutations were as follows: USH1G (1 patient), CLRN1 (1 patient), PCDH15 (2 patients), and USH1C (4x)." (PMID 28944237, 2017). "A total of 19 CLRN1 mutations have been documented in patients with USH or RP around the world (Human Gene Mutation Database; Leiden Open Variation Database for Usher Syndrome)." (PMID 23304067, 2012). "In contrast to the lack of a retinal phenotype, but similar to most other mouse models of Usher syndrome, the Clrn1 KO mouse exhibits significant structural and functional hearing deficits." (PMID 19680541, 2009). "Besides the USH2A gene, Usher syndrome also was caused by ABHD12 (1; 5%), CLRN1 (1; 5%), and MYO7A (8; 40%) genes." (PMID 30374144, 2018). "Genome-wide linkage analysis revealed two small candidate regions on chromosome 3, one containing the USH3A gene CLRN1, which has never been associated with Usher syndrome in Saudi Arabia." (PMID 28469144, 2017).
Usher syndrome (continued). "However, given the interspecies difference in phenotypic presentation observed with Clrn1, we cannot exclude the possibility that pathogenic CLRN2 mutations in humans might give rise to an Usher syndrome‐like phenotype." (PMID 31448880, 2019). "At least 9 causative genes have been found and identified to be responsible for Usher syndrome: Five for USH1 (MYO7A, USH1C, CDH23, PCDH15, and USH1G), three for USH2 (USH2A, ADGRV1, and WHRN) and one for USH3 (CLRN1)." (PMID 38984112, 2024). "In mouse photoreceptors, several protein complexes involved in Usher syndromes, a group of genetic diseases that exhibit photoreceptor degeneration, are localized at or near the CC/TZ including Usher 1 syndrome (USH1) proteins, USH2 proteins, and the USH3 protein clarin-1." (PMID 27737822, 2016).
hearing loss (15 papers, 2012 to 2026). "Variations in CLRN1 directly influence the progression and severity of hearing loss, retinitis pigmentosa, and vestibular dysfunction." (PMID 40149483, 2025). "CLRN1 variants are usually associated with USH3, which is characterized by post-lingual hearing impairment with a progressive nature, variable vestibular dysfunction, and variable onset of RP." (PMID 35651951, 2022). "In summary, virally mediated gene delivery in a mouse model of progressive hearing loss in USH3 can 1) effectively prevent the onset of deafness associated with a Clrn1 mutation and 2) deliver robust, long-term hearing preservation if the treatment is applied prior to the onset of the phenotype." (PMID 29044151, 2017). "Finally, USH3 is characterized by variable onset of progressive hearing loss, variable onset of RP, and variable impairment of vestibular function and is caused by mutations in the USH3A (clarin-1) gene, located on 3q21-q25." (PMID 22952768, 2012). "The vast majority of CLRN1 variants cause USH3, with a variable age of hearing loss onset and a progressive nature." (PMID 39596563, 2024). "Altogether, while mutations in CLRN1 unambiguously lead to USH3A, current findings suggest that CLRN2 mutation most likely causes non‐syndromic hearing loss." (PMID 31448880, 2019). "We screened 500 normal Chinese individuals and 122 unrelated Chinese families with apparent hearing loss but did not detect the loci of CLRN1: c.474T > A (or c.302T > A) by Sanger sequencing." (PMID 39304915, 2024). "Mutations in CLRN1 resulted in USH3A, which is characterized by progressive hearing impairments." (PMID 38137568, 2023).
retinitis pigmentosa (12 papers, 2009 to 2025). Retinitis pigmentosa (RP) is an inherited retinal dystrophy leading to progressive loss of the photoreceptors and retinal pigment epithelium and resulting in blindness usually after several decades. "CLRN1 is known as the causative gene product of Usher syndrome type IIIa which causes deafness and visual impairment phenotypically similar to retinitis pigmentosa." (PMID 25807145, 2015). "In contrast to all other known disease-causing mutations resulting in retinitis pigmentosa (RP), Clrn1 mRNA expression was restricted to the inner nuclear layer (INL) of the retina, and was undetectable in photoreceptor or retinal pigmented epithelial (RPE) cells." (PMID 19680541, 2009).
deafness (11 papers, 2009 to 2026). An inherited or acquired condition characterized by the complete loss of the ability to hear from one or both ears. "Specifically, both the Clrn1 KO and N48K knock-in mouse models of USH3A present with an early-onset hearing loss and profound deafness by postnatal day P30." (PMID 40067805, 2025). "Based on the results from our report and characteristics of USH3, we believe that clarin-1 is well suited for further development as a gene-therapy strategy to prevent deafness associated with USH3." (PMID 29044151, 2017). "Our data suggest that CLRN1, the protein implicated in Usher syndrome type 3 which caused progressive blindness and deafness in humans, is an inner retinal protein (at least in mice) produced by the retinas resident radial glia, Müller cells." (PMID 19680541, 2009). "Since the USH3 human combined blindness and deafness phenotype is progressive, we studied Clrn1 KO mice up to 2 years." (PMID 19680541, 2009). "Mutations in the CLRN1 gene cause Usher syndrome type 3 (USH3), a human disease characterized by progressive blindness and deafness." (PMID 19680541, 2009). "By revealing a functional, compensatory interplay between clarin-1 and clarin-2, this study reframes CLRN1-associated deafness as a network-dependent disorder and provides a mechanistic basis for genetic stratification and therapeutic directions in USH3 and related sensorineural hearing loss." (PMID 41572507, 2026). "In addition, mutations in three corresponding genes (usherin USH2A, G protein-coupled receptor 98; GPR98, and deafness, autosomal recessive 31; DFNB31) have been reported so far in USH2, and USH3 is caused by mutations in the clarin 1 (CLRN1) gene." (PMID 24618850, 2014). "In addition, mutations in MYO7A, USH1C, DFNB31, CIB2, CDH23 and PCDH15 were also reported in non-syndromic deafness without retinal degeneration and mutations in USH2A and CLRN1 have been reported in patients with isolated RP or retinal dystrophies and no deafness." (PMID 25211151, 2014). "Thus, in the Clrn1 KO mouse we have established another model of USH where deafness is apparent, but blindness is absent." (PMID 19680541, 2009).
Usher syndrome type 3 (7 papers, 2009 to 2024). "Usher syndrome type 3 (USH3) is an autosomal recessive inherited disorder caused by pathogenic variants in the CLRN1 gene." (PMID 39304915, 2024). "Usher syndrome type 3 (USH3) is an autosomal recessively inherited disorder caused by mutations in the gene clarin‐1 (CLRN1), leading to combined progressive hearing loss and retinal degeneration." (PMID 31625146, 2020). "Usher syndrome type 3 is caused by mutations in the USH3A (clarin-1) gene, mapped to 3q21-q25." (PMID 21738395, 2011). "Mutations of clarin 1 (CLRN1) cause Usher syndrome type 3 (USH3)." (PMID 19753315, 2009). "However, bi-allelic variants in CLRN1, LSS, and TUB have been associated with AR Usher syndrome type 3, congenital cataract, or RP, respecitvely." (PMID 38785568, 2024).
Usher syndrome type IIIA (6 papers, 2015 to 2026). "In humans, recessive CLRN1 mutations cause Usher syndrome type IIIA (USH3A, MIM276902), characterized by post‐lingual, progressive hearing loss, and variable balance and vision loss deficits." (PMID 31448880, 2019). "Usher syndrome type IIIA is caused by mutations in CLRN1 encoding clarin-1." (PMID 33204247, 2020). "An example is clarin-1 N48K in Usher syndrome type IIIA (USH3A)." (PMID 42133691, 2026).
retinal degeneration (5 papers, 2009 to 2025). Degeneration of the retina. "If CLRN1 expression in humans is comparable to the expression pattern observed in mice, this is the first report of an inner retinal protein that, when mutated, causes retinal degeneration." (PMID 19680541, 2009). "This represents the first animal model of USH3 that displays retinal degeneration, allowing us to investigate the impact of Clrn1 absence on the retina and the cells that contribute to progressive vision loss." (PMID 38464015, 2024). "Usher syndrome type III (USH3) is caused by clarin-1 (CLRN1) gene mutations, leading to progressive sensorineural hearing loss and retinal degeneration, with variable vestibular dysfunction." (PMID 26881841, 2016). "Clrn1 KO mice do not develop a retinal degeneration phenotype, but exhibit progressive loss of sensory hair cells in the cochlea and deterioration of the organ of Corti by 4 months." (PMID 19680541, 2009). "Photoreceptors in the Clrn1 knockout mice remained anatomically and physiologically normal, without exhibiting any phenotypic characteristics of retinal degeneration." (PMID 19680541, 2009). "For reasons that remain unclear, the Clrn1 knockout mouse does not have a retinal degeneration phenotype but does become deaf soon after birth." (PMID 19680541, 2009).
retinal diseases (3 papers, 2021 to 2025). "A subset of patients was screened for mutations in retinal disease genes, and mutations in the following genes were found: three cases with USH2A; three cases with EYS; one case each with USH3A (CLRN1), DHX38, RHO, RPGR, and RP9." (PMID 33037922, 2021). "The role of Müller glia in maintaining photoreceptor health and contributions to USH3 pathology is understudied, in part as Clrn1 mutant mice - the traditional experimental model used to study retinal diseases - do not phenocopy the photoreceptor loss of USH3 patients." (PMID 38464015, 2024).
sensorineural hearing loss (3 papers, 2016 to 2026). "Usher syndrome type III (USH3A) is an autosomal recessive disorder caused by mutations in clarin-1 (CLRN1) gene, leading to progressive retinal degeneration and sensorineural deafness." (PMID 26881841, 2016).
microtia (2 papers, 2020 to 2022). "CLRN1 is associated with Usher syndrome type 3A, which is a progressive hearing and vision loss, and was thus proposed as a novel candidate gene for determining microtia in sheep." (PMID 36085023, 2022). "When genotyping 40 individuals (20 with microtia and 20 normal) of the Valle del Belice sheep breed, a strong marker within intron 3 of CLRN1 was identified." (PMID 36085023, 2022).
auditory neuropathy (1 paper, 2025). A hearing disorder characterized by impaired transmission of signals through the auditory nerve, resulting in mild to severe hearing loss and poor speech perception. "Finally, neural factors, such as cochlear nerve hypoplasia or auditory neuropathy, as was observed in the subjects with pathogenic variants in CLRN1 and OPA1, respectively, may result in poorer outcomes." (PMID 40268851, 2025).
hearing (1 paper, 2024). "Our results therefore support those reported by others that relatively mild CLRN1 variants can cause non-syndromic RP or RP with late-onset hearing loss." (PMID 39596563, 2024).
CLRN1 also shares sentences with these, for which no sentence is quoted: Hearing impairment (4 papers); autosomal recessive inherited disorder (2); Blindness (2); tumor (2); Ataxia (1); Bardet-Biedl syndrome (1); ciliopathy (1); colorectal carcinoma (1); cone dystrophy (1); congenital stationary night blindness (1); deafness, autosomal recessive 31 (1); formiminoglutamic aciduria (1); genetic diseases (1); hypoparathyroidism (1); lymphoma (1); macular degeneration (1); neurodegenerative disease (1); nonsyndromic deafness (1); optic atrophy (1); polyneuropathy (1); renal dysplasia (1); Retinal dystrophy (1); Sensorineural hearing impairment (1); Stickler syndrome (1); Usher syndrome type 1G (1).